CD4 (CD4 molecule)
Diseases named in the same sentence as CD4 in open-access papers (continued):
Sharing a sentence is not in itself a finding about the gene and the disease.
infection (continued). "Our first report in RAG-hu mice showed a lack of CD4+ T cell loss in the blood through 24 weeks of infection with NLENG1-IRES, a reporter strain of HIV-1 that expresses GFP and places the nef gene under the control of an IRES element in the background of the CXCR4-tropic strain NL4-3." (PMID 21835012, 2011). "Also, the efficient infection of B cells by FV, which then present FV antigens to specific CD4+ T cells, may contribute to enhance Tfh differentiation." (PMID 21943070, 2011). "However CD4+ “helper” T cells contribute to the function of CD8+ T cells in such infections." (PMID 21283759, 2011). "We found that MDDCs could be activated by both dimorphic forms of P. marneffei for significantly promoting HIV-1 trans-infection of CD4+ T cells, and the Candida albicans (C. albicans), which has been proved to possess the similar capacity, was used as control." (PMID 22110688, 2011). "As expected, depleting CD4+ T cells resulted in greater bacterial burden in both wildtype as well as Irgm1/m3(-/-) mice relative to control mice of the same genotype, confirming that the adaptive immune response contributes to immune clearance at later times in the course of the infection." (PMID 21731484, 2011). "Infection of IL17−/− mice with M. tuberculosis revealed that IL-17 was not essential to control the growth of M. tuberculosis during acute infection suggesting that IFN-γ-secreting CD4+ and effector CD8+ T cells were sufficient to inhibit mycobacterial replication in the absence of IL-17." (PMID 21603219, 2011). "To model this function in vitro, we have previously developed a virus suppression assay that determines whether SIV-specific CD8+ T-cell clones can reduce the spread of SIV in autologous CD4+ T-cell clones exposed to SIVmac239 at relatively low multiplicities of infection." (PMID 21886812, 2011). "Combined, these data suggest that in early infection, viral replication and target cell infection and destruction are similar in the two infections, yet eventually, viremia is controlled and central memory CD4+ T cells begin to recover in SHIV-infected macaques." (PMID 21464951, 2011). "In this study, we have demonstrated that DC-SIGN-mediated enhancement of infection with HIV-1 is the result not only of increasing the concentration of virus at the cell surface as suggested previously but also of the increased affinity of the DC-SIGN:gp120 complex for CD4." (PMID 22163292, 2011). "The proportion of CD4+ T cells also appeared to decrease by day 28 following infection, which could be due to an increase in the proportion of B cells, a phenomenon that has been observed in other murine models in which mice are infected with intracellular bacteria, such as Mycobacterium." (PMID 21765931, 2011). "Specifically, effector memory CD4 T cells may play important roles in protection against infection." (PMID 21364749, 2011). "Because cathepsin B protease, a natural ligand of cystatin C, was upregulated in HeLa cells, we speculated that the high levels of cathepsin B activities were inhibitory to the CD4-independent infection and that cystatin C enhanced the infection by impairing the excessive cathepsin B activity." (PMID 21541353, 2011). "Indeed, cells with low CD4 expression have been suggested torequire high CCR5 for infection." (PMID 21647388, 2011). "Similarly, immunization of chronically infected, ART treated patients with HIV antigens does not result in the generation of significant HIV-specific CD4+ T cell responses, suggesting that HIV-specific CD4+ T cells are dysfunctional or preferentially depleted in infection and fail to recover." (PMID 21752277, 2011). "Of the total lymphocytes isolated from granulomatous portions of the lungs, the percentage of CD4+ T cells declined from 63 per cent (4 weeks) to 18 per cent (12 weeks), and then increased moderately to about 25 per cent of total lymphocytes at 16 weeks of infection." (PMID 22645653, 2011).
infection (continued). "The low CD4+ T cell counts associated with a Bx genotype inabsence of Bw4:C1 could result from a higher rate of CD4+T cell decline during acute and/or chronic infection, or simply from a longertotal duration of infection, a distinction that cannot be made bycross-sectional analyses." (PMID 21347267, 2011). "Second, the higher susceptibility of Myd88−/− mice could be directly attributed to the defective activation of CD4+ T cells demonstrated here, as this cell population has also been demonstrated to be essential for resistance to infection, probably through IFN-γ and TNF-α secretion." (PMID 20442858, 2010). "Factors contributing to the elicitation of broadly NAb may include the magnitude and duration of viral replication, the preservation of CD4+ T cells, the degree of B-cell depletion, the conformation of Env during primary infection, or the appearance of certain envelope structures during infection." (PMID 20824092, 2010). "It is presently unclear whether infection, provirus formation, or subsequent reporter gene expression are inhibited during the 48 h of coculture of activated CD4+ T cells with Jurkat effector cells; we are currently examining the reasons for this inhibitory effect." (PMID 20195464, 2010). "The restricted expression of CCR5 mainly on memory CD4+ T cells, but broader expression of CXCR4 on both memory and naïve subsets, is thought in part to underlie the accelerated disease progression seen in individuals in whom CXCR4-using HIV-1 variants emerge late in the course of infection." (PMID 20865163, 2010). "Molecular analyses of subjects with acute HIV infection have indicated that productive infection arises from a single infectious virus, and other studies suggest that the first cells to be infected in the mucosa are resident memory T cells expressing CD4 and CCR5." (PMID 20569472, 2010). "Therefore, under rapid T cell turnover, DCs could be indispensable to permitting continuous infection of new CD4+ T cells." (PMID 20360840, 2010). "The average turnover rate of CD4+ T cells from control c1 was always higher than that of the other individuals, irrespective of the model used, which may be a sign of an immune response to an infection in c1 (see also below)." (PMID 20140186, 2010). "Thus, early after Raji/CD4 cell addition, cell free infection may predominate, but later transmission through the VS may be favored." (PMID 20195464, 2010). "Thus, a significant increase in the number of caspases-3/7+CD4+ DCs could be observed 24 h post infection." (PMID 21124820, 2010). "Interestingly despite dramatic shifts in the percent and absolute number of CD4+ T cells among splenocytes, the percent Foxp3+ Tregs among CD4+ T cells remains remarkably stable and essentially unchanged at approximately 10% throughout the infection." (PMID 20714351, 2010). "Multiple mechanisms have been proposed to explain infection-induced immunosuppression, including an imbalance in the cellular T helper cell (Th1/Th2) or cytokine profile, induction of anergy, depletion of effector cells and most recently the activation of CD4+CD25+ Tregs." (PMID 20064232, 2010). "With HIV primarily targeting CD4+ cells, (activated lymphocytes), these factors mean that there is, typically, a large population of targets, (i.e. potential host cells), for the virus to infect and, therefore, a massive infection in the tract even in the early stages of the infection." (PMID 20875154, 2010). "Furthermore, in contrast to HIV-DC-CD8+ T cells, HIV-C-DC-boosted CD8+ T cells also elicited antiviral activity, when stimulated CD4+ T cells were infected 3 days prior addition of the specific CTLs, thus inhibiting an already on-going infection of the CD4+ T cells." (PMID 20442876, 2010).
infection (continued). "If such longer-term infected cells have mature infectious HIV-1 attached to the cell surface at these polar caps then subsequent contact with uninfected CD4+ T cells may allow rapid infection of the target cell by direct-virion fusion with the target cell plasma membrane." (PMID 21994681, 2010). "To determine whether the ability of Tax to enhance infection in Jurkat-Raji/CD4 cocultures was simply due to cell-cell aggregation, we examined whether inducing a synapse between Jurkat cells and Raji/CD4 cells would affect cell-to-cell infection." (PMID 20195464, 2010). "HAdV shedding from the lower GI tract may occur in healthy adults, but is more common in children (where it may represent a primary infection), immunocompromised individuals, and persons with HIV infection, particularly those with symptomatic infection and low CD4 counts." (PMID 20593015, 2010). "Therefore, targeting of CD8α+ DCs by Ye may result in immune evasion of the pathogen as infection control requires CD4+ Th1 host responses." (PMID 21124820, 2010). "However, citations present in futureMEDLINE suggest the CD4 receptor may play an auxiliary role in Visna-Maedi virus infection, and that CD4+ T-cells play an important role in the immune response to this infection." (PMID 20859853, 2010). "However, by day 10 of the infection CD4+ numbers had begun to increase dramatically in the UGT." (PMID 21079691, 2010). "In a general population of HIV-infected individuals, patients presenting with an unknown duration of infection will have even fewer CD4 cell measurements prior to initiating cART making it more difficult to estimate a reliable pre-cART CD4 cell slope for such patients." (PMID 20186270, 2010). "Association between multiplicity of infection of HIV-1 (BaL) required for the 50% inhibitory effect of PBMC (Infectivity) and the proliferative response, percentage of IFNγ produced and CD25+FoxP3+ T cells (T regs) of CD4+ T cells; analysis by Mann Whitney test." (PMID 19956755, 2009). "Thus, the detection of CD4+ T cell responses following immunization with strains of SIV that are limited to a single round of infection may reflect the uncoupling of CD4+ T cell activation from ongoing infection and destruction of these cells." (PMID 19165322, 2009). "For example, after the cells capture and bind HIV-1, a rapid transfer (i.e. early transfer or trans infection) occurs when the virus on the surface of immature DCs or located within endosomal compartments is transported to the DC/T-cell synapse and transmitted directly to CD4+ T cells." (PMID 19468304, 2009). "When considering expansion of CD4-guided treatment initiation, thresholds may furthermore need to be differentiated between populations, to account for geographical and age/sex differences in pre-infection distributions." (PMID 19536329, 2009). "In line with this, CD4 T cells with proliferative capacity showed higher accumulation at the site of infection than CD8 T cells two weeks post infection (although we can exclude that this bias in CD4 proliferation may in part reflect a bias inherent in the CD4 prime/boost mechanism)." (PMID 19357780, 2009). "Although class II MHC tetramer-based analysis may open a new avenue to further understand differentiation and evolution of antigen-specific CD4 T-cell subpopulations in the context of vaccinations or infections, fundamental aspects of the tetramer application remain to be characterized." (PMID 19730727, 2009). "Interestingly, this correlated with a beneficial effect of the vaccine on infection course, as demonstrated by a decrease of viral RNA in plasma and proviral load in the PBMCs and an increase of circulating CD4+ T-lymphocytes (Pistello, manuscript in preparation)." (PMID 19284578, 2009).
infection (continued). "Interestingly, the CFU levels at six weeks post infection in the vaccine groups directly correlated with the ESAT-6 CD4 T cell response (R2 = 0.78), in agreement with previous work indicating that the ESAT-6 specific response can be used as a predictor for bacterial load." (PMID 19357780, 2009). "We show here, that following its natural route of infection, wild-type MV induces a strong and broad activation of the immune system, the generation of MV-specific humoral and cellular anti-viral responses, accompanied by an increase in the frequency of regulatory CD4+CD25+Foxp3+ T cells." (PMID 19319188, 2009). "Furthermore, we showed that individuals from IND group presented more TCM CD4+ T cells, which may induce a regulatory mechanism to protect the host against the exacerbated inflammatory response elicited by the infection." (PMID 19742301, 2009). "Although high RNA is the earliest predictor of clinical progression after HIV seroconversion, for populations of treatment-naïve patients during stable infection or with unknown date of seroconversion, CD4 surpasses RNA as a prognostic indicator and screening tool to select patients in need of ART." (PMID 19536329, 2009). "We employed mice with healed L. major infections to mimic leishmanization, and found tissue-seeking, cytokine-producing CD4+ T cells specific for Leishmania at the site of challenge by infected sand fly bite within 24 hours, and these mice were highly resistant to sand fly transmitted infection." (PMID 19543375, 2009). "In IgD deficient mice, however, infection did not increase the CD4+ T cell population." (PMID 19859584, 2009). "CD4 T cells function through their capacity to help B cells produce antibodies, to activate macrophages for enhanced microbicidal activity, to recruit leukocytes to infection/inflammation sites, and through their production of cytokines and chemokines to orchestrate adaptive immune responses." (PMID 19730727, 2009). "CD4 cell count data could help to exclude some individuals with long-term infections but, in addition to the logistical challenges of doing this, the variability in CD4 counts within and between individuals would make such a correction technical involved and likely incomplete." (PMID 19479050, 2009). "Moreover, production of IL-10 during the early acute phase of infection is associated with an increased proportion of splenic CD4+CD25+ T cells in non-lethal P. yoelii infection." (PMID 19680449, 2009). "An alternative hypothesis is that IFN-γ producing CD4+ T cells are sequestered at the tissue site of infection, rather than in the blood, causing a paradoxically low level of IFN-γ production to antigen stimulation." (PMID 19065267, 2008). "A decrease of RD1-specific CD4+ T-cell effector responses has been reported also in animal models of M. tuberculosis infection in which a decrease in responses in mononuclear cells from both the lymph nodes and lungs after the acute phase of infection was shown." (PMID 18226199, 2008). "Indeed, transfection of CD4-positive CCR5-negative cells with mutant CCR5 unable to transduce signals made such cells fully susceptible to infection with R5 HIV-1 (R5 viruses infect cells expressing CD4 and CCR5, while X4 viruses infect cells with CD4 and CXCR4)." (PMID 18808680, 2008). "To substantiate this finding, we investigated whether the TLR agonists induced changes influence HIV replication at the level of transcription: for that purpose CD4+ T-cells were infected overnight and spreading infection was inhibited by adding the fusion inhibitor enfurvitide." (PMID 18431484, 2008). "We raise the possibility that CD4 T cells arrested in the G1 phase of the cell cycle may contribute to the “hidden reservoir” of HIV-infected cells which persists through the course of infection." (PMID 18698365, 2008).
infection (continued). "DC-T cell conjugates facilitate productive infection in CD4 T cells, and dissemination of the infection to the draining lymph nodes and subsequent other lymphoid tissue compartments is ensured by virus-carrying DCs together with infected macrophages and CD4 T cells." (PMID 18974890, 2008). "Thus, infection of naïve cells by R5broad viruses may interfere with CD4+ T cells production, and thus account for the rapid disease progression observed in children harbouring these viruses." (PMID 18820725, 2008). "Therefore, the fMLF peptide might have a partially inhibitory effect on infection of NP-2/CD4/CCR5 cells with the CBL23 and mndGB-1 strains." (PMID 18577234, 2008). "In addition, approximately 1% of all splenic CD4+ T cells were IFNγ+ at 12 hours after infection." (PMID 18404208, 2008). "None-the-less, a massive loss of CD4+ T cells in the gut occurs within 2 weeks of infection." (PMID 18451982, 2008). "When NP-2/CD4/FPRL1 cells were exposed to these isolates, the cells were found to be clearly susceptible to AG204, AG206, HCM308, HCM342, and mSTD104 isolates: 20, 30, 15, 40, and 60% cells, respectively, became HIV-1 antigen-positive by IFA on day 6 after infection and syncytia were formed." (PMID 18577234, 2008). "Reisolates obtained early in infection (2-week isolates from nine macaques and 3 or 4-month isolates from four macaques) showed a more pronounced CD4-independence (CD4-independent-HIGH) since virus production and/or syncytia induction could be detected directly in NP-2/CCR5 cells." (PMID 17645788, 2007). "However, the persistence of preintegrated forms of HIV-1 could be explained by the de novo infection of resting CD4+ T cells due to residual viral replication." (PMID 17727722, 2007). "CD4-independent infections may conceivably have important consequences." (PMID 17645788, 2007). "Alternatively, the differences in viral replication in the different gut tissues could be the result of different levels of infection due to differences in the amount of infectable cells (i.e. CD4+ cells) in those tissues, or differences in the amount of viral RNA produced by each infected cell." (PMID 18053211, 2007). "At the acute stage, a massive infection and subsequent destruction of 60–80% of memory CD4+ T cells takes place in the mucosa and lymph nodes, with initially little effect upon the peripheral blood CD4+ T cell numbers, mainly because local memory CD4+ T cell numbers are low." (PMID 17892568, 2007). "Using this experimental model, we were able to lend support to the hypothesis that the timing of accumulation of the parasite load can be a key factor influencing the differentiation and proliferation of CD4+ T cell-dependent specific CD8+ cytotoxic T cells following infection with a human pathogen." (PMID 17460760, 2007). "Our findings clearly demonstrated that both infected CD4+ T cells and LC were capable of migrating out of the vaginal epithelium, and thus both may be responsible for amplifying local infection and subsequently disseminating infection systemically." (PMID 17306567, 2007). "The inoculum virus (SIVsm isolate SMM-3) and reisolates obtained early in infection often showed a pronounced CD4-independence since virus production and/or syncytia induction could be detected directly in NP-2 cells expressing CCR5 but not CD4 (CD4-independent-HIGH)." (PMID 17645788, 2007). "Both macaques also developed a rapid decrease in peripheral blood levels of CD4+ T cells from an average of 914 ± 121 cells/μL (CD4:CD8 ratio of 0.715 + 0.2) before inoculation to persistently low levels of 75 – 150 cells/μL (CD4:CD8 ratio of 0.01 – 0.09) blood during primary infection." (PMID 17132170, 2006). "Indeed, the ability to enhance CD4+ T helper cell responses in the chronic phase of infection has been demonstrated, but whether this will enhance CD8+ T cell function requires additional studies." (PMID 15526059, 2004).